AKT1 (AKT serine/threonine kinase 1)
Diseases named in the same sentence as AKT1 in open-access papers (continued):
Sharing a sentence is not in itself a finding about the gene and the disease.
breast cancer (continued). "Overexpression of AKT1 has been reported in gastric and breast cancers." (PMID 28513565, 2017). "The results of SAHA treatment in TRAIL DR5-silenced MCF-7 cells, a ER-positive breast cancer cell line, displayed that AKT1 and ATK2 play important regulatory roles in SAHA-TRAIL DR5 induced autophagy, but AKTs had slight effects on monitoring autophagy in ER-negative cells such as MDA-MB-231." (PMID 29018571, 2017). "We conclude that AKT isoforms play specific roles in different steps of breast cancer progression, with AKT1 involved in the local tumor growth and AKT2 involved in the distant tumor dissemination, having AKT2 a poorer prognostic value and consequently being a worthwhile target for therapy." (PMID 28287129, 2017). "AKT1 mRNA is the major isoform expressed in murine mammary tumour cells." (PMID 28082369, 2017). "There was a significant difference in the genotype distribution of the PTEN rs701848 and AKT1 rs2494752 polymorphisms between the breast cancer patients and the non-cancer controls." (PMID 28423632, 2017). "Interestingly, expression of constitutively active AKT1 promoted metastasis in a murine melanoma model in contrast with the reduced metastasis observed in murine mammary cancer models." (PMID 28082369, 2017). "Since AKT1(E17K) expression in the mouse mammary gland does not lead to tumor formation, this begs the question as to why this mutation is detected in 4-8% of breast cancer patients." (PMID 27004402, 2016). "Finally, we analyzed mRNA expression and reverse-phase protein array (RPPA) data from the breast cancer TCGA data set for tumors harboring AKT1(E17K)." (PMID 27004402, 2016). "Mutation of AKT1, a downstream molecule of PI3K, occurs in 5–24% breast cancers." (PMID 25816324, 2015). "In contrast to SF3B1 mutant unselected breast cancers, no papillary carcinomas in this series were found to harbour AKT1 hotspot mutations." (PMID 25424858, 2015). "As expected, the total levels of the AKT1 protein are elevated in all mammary tumor subtypes, but the activation of this kinase varies significantly and is highest in tumors with a known hyperactivation of the PI3 kinase in response to ERBB2 overexpression or loss-of-function of PTEN." (PMID 24628780, 2014). "AKT1 (1.4%) and PTEN (2.3%) mutations were determined to be restricted to ER+ breast cancers." (PMID 25051360, 2014). "Moreover, it has been demonstrated that JAK2/STAT5 signaling and AKT1 play essential roles during mammary tumor initiation in various murine cancer models." (PMID 24628780, 2014). "As an example, a recent study in breast cancers has identified additional driver mutations in AKT1 that are not located in hotspot regions frequently tested." (PMID 24912489, 2014). "Similarly, the levels of Akt2 were undetectable in MTB-IGFIR/Akt2−/− mice while Akt1 levels were similar in MTB-IGFIR mammary tumors and mammary tumors from MTB-IGFIR/Akt2−/− mice." (PMID 23919516, 2013). "Three Akt isoforms are expressed in breast cancer cells (e.g. Akt1, Akt2,and Akt3)." (PMID 23874830, 2013). "The mutational and mRNA expression status of PIK3CA, PIK3R1 and AKT1, and expression status of other genes involved in the PI3K pathway (EGFR, PDK1, PTEN, AKT2, AKT3, GOLPH3, WEE1, P70S6K) were assessed in a series of 458 breast cancer samples." (PMID 24229379, 2013). "The frequencies of PIK3CA, PIK3R1 and AKT1 alteration differ according to breast cancer subtypes." (PMID 24229379, 2013).
breast cancer (continued). "Importantly, cytoplasmic retention of Brca1 is strongly correlated with activated Akt1 in biopsies from sporadic breast cancer patients." (PMID 22481935, 2012). "Interestingly, in patients with low p-Akt1 expression, cytoplasmic Skp2 expression was significantly associated with DFS and OS of patients with breast carcinoma." (PMID 23300741, 2012). "One speculation is that since Akt1 has been shown to block breast cancer cell migration, the presence of a E307K mutant may repress Akt1 activation and promote metastatic growth." (PMID 22103913, 2011). "As with R26-Pik3caH1047R-Cre model mice, but unlike Akt1 transgenics, Pten loss-of-function mutants develop mammary tumors." (PMID 21646685, 2011). "Akt1, a serine-threonine protein kinase member of the PKB/Akt gene family, plays critical roles in the regulation of multiple cellular processes, and has previously been implicated in lactation and breast cancer development." (PMID 21915327, 2011). "As RTK/PIK3CA/AKT1/PTEN and IKK/NFκB are the two most frequently mutated pathways in breast cancer, any crosstalk between them may represent a critical therapeutic target." (PMID 21646685, 2011). "However, it is noteworthy that, in a number of studies, the oncogenic kinase AKT1 has been shown to be upregulated in 40-60% of sporadic breast cancers and 40% of sporadic ovarian cancers." (PMID 21321378, 2010). "Because AKT1 activity is inducible by hormones, it is tempting to speculate that, for certain people, hormonal treatments could lead to high and chronic activation of AKT1, thus altering the functions of BRCA1, and therefore to predispose to breast cancer." (PMID 21321378, 2010). "Therefore the high frequency of AKT1 activation in sporadic breast cancer opens promizing new avenues for therapy." (PMID 21321378, 2010). "Overall, we detected the four AKT1 E17K mutations in the breast cancers (4/93; 4.3%), but none in other cancers." (PMID 18392055, 2008). "Interestingly, 21% (7/34) of the genes that positively correlated with AKT1 expression in a study by Creighton and co-workers, correlated positively with AKT1 expression also in our rapamycin-treated breast cancer cell lines." (PMID 18652687, 2008). "This led to the hypothesis that activation of Akt1 induced aerobic glycolysis in these mammary carcinomas." (PMID 18700973, 2008). "Thus, activated Akt1 plays a functional role in promoting the development of HER-2 positive mammary tumours." (PMID 16168126, 2005). "We aimed to examine the role of Akt-1 in breast cancer patients, by determining whether the expression (Akt-1) and/or activation (pAkt) were related to prognostic markers and survival." (PMID 11870534, 2002). "In this study, breast cancer tissues were not categorized by AKT1 mutation status." (PMID 40135844, 2025). "In this study, we sought to compare the concordance of pathogenic alterations in PIK3CA, AKT1, AKT2, AKT3, and PTEN detected by tissue-based FoundationOne®CDx and blood-based FoundationOne®Liquid CDx in contemporaneous samples collected from patients with breast cancer." (PMID 40597213, 2025). "Due to activating mutations in PIK3CA and AKT1, and loss-of-function mutations in the tumor suppressor PTEN, it is frequently hyperactivated in triple-negative breast cancer, making this subtype of breast cancer particularly aggressive and resistant to conventional therapies." (PMID 40647529, 2025). "No AKT1 E17K mutation was found in 75 HER2 + or 111 HR-/HER2-breast cancers." (PMID 38875362, 2024). "More importantly, we present a combination strategy of STING agonists and AKT1 inhibitors that could block the positive feedback loop to maximize the activation of cGAS‐STING signaling in endocrine‐resistant breast cancer cells, overcoming endocrine resistance." (PMID 39023171, 2024). "Therefore, targeting AKT1 could have a significant impact on improving the treatment outcomes for breast cancer patients." (PMID 39275052, 2024).
breast cancer (continued). "In addition, evidence in hormone receptor positive (HR+) breast cancers suggest potential roles for upstream receptor overexpression (FGFR2) and de novo mutations in RAS, AKT1, AURKA, CCNE2, and/or ERBB2 in the activation of ERK following acquired CDK4i/6i resistance." (PMID 38066089, 2024). "This study highlights the promising inhibitory potential of [125I]anastrozole and [125I]epirubicin, particularly [125I]epirubicin, against AKT1, suggesting that these compounds could serve as valuable leads in the development of new therapeutic agents for breast cancer." (PMID 39275052, 2024). "On the other hand, we suggest that the best effective compound is coptisine targeting AKT1, which can provide a theoretical basis for the further study of the drug-like active compounds and offer molecular mechanisms behind their roles in the treatment of breast cancer." (PMID 36835006, 2023). "Here, we detected activating PIK3CA mutations, AKT1 mutations, and inactivating PTEN alterations in 76 (54%) of an intention-to-treat population of postmenopausal women with ER-positive, HER2-negative advanced breast cancer who had previously been treated with an aromatase inhibitor." (PMID 35671774, 2022). "Whereas miR200a was the predominant Akt1-regulated miRNA identified in breast cancer cells, this, however, was unchanged in the Akt-suppressed TRAMP prostates suggesting that the Akt1-regulated miRNAs in different cancer types may vary based on their origin and/or specific mutations that they hold." (PMID 35406397, 2022). "In addition to an expected positive relationship between the status of AKT1 and co-expressed cellular genes, our study unexpectedly discovered an inherent role of AKT1 in inhibiting the expression of a subset of genes in both unstimulated and growth factor stimulated breast cancer cells." (PMID 35892586, 2022). "A similar concordance level was observed for advanced breast cancer patients, where an overall concordance of up to 95% (negative and positive) was observed for the detection of mutations from the four major driver genes of breast cancer—PIK3CA, ESR1, AKT1, and HER2." (PMID 35805046, 2022). "However, the nature of AKT1-specific genome-wide transcriptomic alterations in breast cancer cells and breast cancer remains unknown to this point." (PMID 35892586, 2022). "In addition, AKT1 was revealed that it could be upregulated by SET domain containing 5 in breast cancer to stimulate tumor growth and metastasis." (PMID 33511213, 2021). "For instance, TNBC patients bearing mutations in PIK3CA, AKT1, and ESR1, as well as EGFR amplifications, may be treated with different drugs to those that are used to treat other subtypes of breast cancer (BRCA) and Non-Small Cell Lung Cancer (NSCLS), respectively." (PMID 34680239, 2021).
breast cancer (continued). "Recently, inhibition of Akt-1 has been shown to induce metastasis through EGFR-mediated β-catenin nuclear accumulation in breast cancer cells, suggesting that the concomitant inhibition of Akt-1 and EGFR might be effective to limit the metastatic potential of Akt-1 inhibition." (PMID 34946644, 2021). "Interestingly, the dichotomic role of AKT1 is not limited to breast cancer." (PMID 31752925, 2019). "Therefore, we determined whether the increased phosphorylation levels of EGFR at Tyr1068 and EGFR total protein in Akt1 impaired breast cancer cells was due to the reduction in degradation through inactivating PIKfyve." (PMID 30445978, 2018). "Given that inhibition of Akt1 enhanced breast cancer metastasis in mice, and many pan-AKT inhibitors are currently undergoing clinical trails for breast cancer treatment, it is of particular importance to determine whether such inhibitors may induce metastasis in the treatment of breast cancer." (PMID 30445978, 2018). "Therefore, we concerned about whether β-catenin nuclear accmulation as an alternative pathway was responsible for breast cancer metastasis induced by Akt1 inhibition." (PMID 30445978, 2018). "Indeed, an increased EGFR co-localization with the early endosomes marker EEA.1 could be detected in MCF-7 and MDA-MB-231 cells treated with Akt1 siRNA, suggesting that PIKfyve activity was inhibited when Akt1 was knocked down in breast cancer cells." (PMID 30445978, 2018). "Furthermore, the tyrosine kinase inhibitor of EGFR may provide therapeutic benefits by limiting the metastatic potential when Akt1 inhibitor was used to treat breast cancer." (PMID 30445978, 2018). "AKT1 might be a binding partner of RhebL1 in breast cancer cells." (PMID 28209923, 2017). "Moreover, Pipp-deficient mammary cancer cells exhibited reduced cell migration and invasion in vitro, a defect rescued by the shRNA-mediated knockdown of Akt1 but not Akt2." (PMID 28082369, 2017). "However, the AKT1 mutation and the methylation profile in its promoter region and their role in breast cancer are still not clear." (PMID 28301567, 2017). "Recently, using insertion mutagenesis in an estrogen-dependent breast carcinoma cell line, a panel of 7 candidate breast cancer anti-estrogen resistant (BCAR) genes were identified that directly underlie estrogen independence leading to tamoxifen resistance, including both EGFR, AKT1, and AKT2." (PMID 24758408, 2014). "In triple-negative breast cancer (TNBC), a previous study demonstrated that exosomal circPSMA1 promotes breast cancer (BC) cell metastasis by sponging miR-637, leading to the activation of the AKT1/β-catenin signaling pathway, which regulates cell proliferation and migration." (PMID 41299506, 2025). "Expert Group Recommendations: It is advised to assess alterations in the PIK3CA, AKT1, and PTEN genes in patients with HR‐positive advanced breast cancer who experience disease progression following endocrine therapy." (PMID 40206206, 2025). "Here, we demonstrated PIPP/PTEN co-depletion further enhanced AKT1 and AKT2 activation in response to growth factor simulation of breast cancer cell lines over single knockdown of either PI-phosphatase." (PMID 41408399, 2025). "By contrast, the authors also found that a WT AKT1 breast cancer xenograft model displayed reduced sensitivity to compound 4, but showed higher sensitive to ARQ092 and capivasertib, both of them are regular pan-AKT inhibitors." (PMID 40478506, 2025). "Regarding the activation of alternative pathways, genetic alterations in AKT1, AURKA, and KRAS have been identified in HR+/HER2− breast cancer that is resistant to CDK4/6is." (PMID 40244377, 2025). "Further molecular docking and dynamics simulations elucidate the binding modes and stability of CNI1-4 with P-gp and AKT1, providing a theoretical framework for its application as an MDR reversal agent in breast cancer." (PMID 40332431, 2025).
breast cancer (continued). "In the breast cancer liquid biopsies that were positive for CAPItello-defined PIK3CA, AKT1, or PTEN alterations, the most frequently observed ESR1 alterations (> 10.0%) were D538G and Y537S." (PMID 40597213, 2025). "UCP2 (uncoupling protein 2), an inner mitochondrial membrane protein, can promote autophagy and endocrine resistance in breast cancer via the ROS1 (ROS proto-oncogene 1, receptor tyrosine kinase)–AKT1 (AKT serine/threonine kinase 1)–MTOR signaling pathway." (PMID 39684286, 2024). "Collectively, these results suggest that the positive feedback loop of inactivated STING signaling and hyperactivated AKT1 has important pathophysiological significance and clinical relevance to endocrine resistance in ER+ HER2– breast cancer patients." (PMID 39023171, 2024). "The protein levels of p‐AKT1 and nuclear IRF3 in 349 ER+HER2– breast cancer samples were evaluated by IHC." (PMID 39023171, 2024). "In conclusion, our work suggests that ropivacaine functions as an AKT1-specific inhibitor, suppressing CSC-like phenotypes in breast cancer cells by inhibiting the NF-κB/GGT1 positive feedback loop." (PMID 38523299, 2024). "Our study found upregulation of AKT1 and AKT3, which are involved in the signaling pathway of PI3K, and previous studies have demonstrated overactivation of the PI3K pathway in breast cancer." (PMID 38225865, 2024). "Multivariate Cox regression analysis showed that the p‐AKT1/nuclear IRF3 score was an independent prognostic factor for the DFS and OS of ER+ HER2– breast cancer patients." (PMID 39023171, 2024). "In untransformed fibroblasts, AKT1 promotes migration, and AKT2 has anti-migratory effects, whereas in breast cancer cell lines, the opposite holds true." (PMID 39614261, 2024). "Notably, treatment with either of these two inhibitors in combination with fulvestrant has shown to prolong progression-free survival against fulvestrant alone in patients with ER/PR positive and HER2 negative advanced breast cancer harboring PIK3CA- or AKT1-mutated or PTEN loss." (PMID 39448637, 2024). "The result shows UISNet selected some important genes such as MAPK1, AKT1, RAF1, that have been proved related to breast cancer prognosis." (PMID 38418940, 2024). "The formation of positive feedback loop between inactivated STING signaling and hyperactivated AKT leads to further amplification of AKT1 phosphorylation and suppressed STING signaling in endocrine‐resistant breast cancer, promoting its endocrine resistance." (PMID 39023171, 2024). "A trial (Capello-291, NCT04305496) assessed the efficacy of capivasertib in combination with fulvestrant in patients with inoperable or metastatic HR-positive and HER2-negative breast cancer, including those with PIK3CA/AKT1/PTEN alterations." (PMID 38791529, 2024). "The AKT1/PI3K pathway is activated in colon cancer by various mechanisms, whereas ERBB signaling has previously shown enrichment by belinostat in breast cancer cells." (PMID 37934338, 2024). "We then assessed the clinical significance of p‐AKT1 and nuclear IRF3 in ER+ HER2– breast cancer patients who received adjuvant endocrine therapy." (PMID 39023171, 2024). "Biological validation of 27 revealed that this small molecule induced dose-dependent inhibition of breast cancer cells (MDA MB-231) and down-regulated the expression of p-AKT1 (Ser473)." (PMID 37513905, 2023). "DDR1 depletion inhibits cell growth and cell cycle progression and enhances the sensitivity of PIK3CA/AKT1 mutant cells to palbociclib in estrogen receptor (ER)-positive, HER2-negative breast cancer." (PMID 37709489, 2023).